GPX4 (glutathione peroxidase 4)
Diseases named in the same sentence as GPX4 in open-access papers (continued):
Sharing a sentence is not in itself a finding about the gene and the disease.
infection (continued). "Further evidence demonstrated that CD4+ and CD8+ T cells lacking GPX4 failed to expand and could not prevent immunity to infection." (PMID 35154262, 2021). "One could expect that the absence of GPX4 in macrophages sensitizes them for lipid ROS and cell death at site of infection resulting in worsening of the outcome." (PMID 33110056, 2020). "Notably, GPX4 levels were not modulated by ubiquitination during infection." (PMID 41356483, 2025).
neurodegenerative disease (33 papers, 2020 to 2026). A disorder of the central nervous system characterized by gradual and progressive loss of neural tissue and neurologic function. "A number of neurodegenerative diseases are associated with increased cell death by oxytosis/ferroptosis, where the decreased function of GPx4 is frequently observed." (PMID 40867843, 2025). "On the other hand, nanoparticles like Lip-1 inhibit ferroptosis by chelating iron and upregulating glutathione peroxidase 4, suggesting a protective role in neurodegenerative diseases." (PMID 40927424, 2025). "Emerging evidence indicates that overexpression of GPX4 inhibits lipid peroxide production and neuronal death, improving motor function in various neurodegenerative diseases such as AD 59-62." (PMID 39431016, 2024). "Given that xCT and GPX4 are currently the main therapeutic targets in controlling ferroptosis, further research into neuroinflammatory and neurodegenerative diseases is warranted." (PMID 38474262, 2024). "Apart from Wnt/β-catenin signaling for the treatment of neurodegenerative diseases, the Nrf2/GPX4 pathway plays a crucial role in cellular defenses against oxidative stress and ferroptosis." (PMID 38424396, 2024). "GPX4-ablation-induced ferroptosis is responsible for cognitive impairment and neurodegeneration in neurodegenerative diseases and can be ameliorated by ferroptosis inhibitors." (PMID 37762411, 2023). "Genetic studies have shown that conditional deletion of GPX4 in mice leads to symptoms resembling neurodegenerative diseases." (PMID 38562992, 2023). "Glutathione peroxidase 4 (GPx4) is an anti-oxidant enzyme which plays a role in neurodegenerative diseases by removing the function of lipid hydrogen peroxide." (PMID 37570686, 2023). "Given that the antioxidant system is decreased in neurodegenerative diseases, we also examined the effect of α-LA on several antioxidant proteins such as GPX4, SOD or PLA2G6 in PKAN fibroblasts." (PMID 37046296, 2023). "The GPX4 protein can inhibit ferroptosis, a phenomenon that has been reported to be related to neurodegenerative diseases (review)." (PMID 35203328, 2022). "AD is a common neurodegenerative disease after rmTBI and has similar characteristics to ferroptosis, such as iron overload, lipid peroxidation, and GPx4 inactivation." (PMID 35836233, 2022). "A recent study found reduced iron accumulation, lipid peroxidation, and GSH and GPX4 in patients with neurodegenerative diseases." (PMID 36090039, 2022). "For example, as a key role of cytoplasmic peroxidation inhibiting protein, Gpx4 has been regarded as a promising therapeutic target of neurodegenerative diseases." (PMID 33996807, 2021). "Ferroptosis can be specifically induced by inhibiting glutathione peroxidase 4 (GPX4) and has also been implicated in a number of pathological processes including neurodegenerative diseases." (PMID 32210808, 2020). "In addition, ferroptosis further exacerbates neuronal death by inducing lipid peroxidation and inhibiting the activity of GPX4, thereby deeply contributing to neurodegenerative diseases." (PMID 40313117, 2026). "FSP1 catalyzes the regeneration of CoQ10 through NAD(P)H, and the FSP1-CoQ10-NAD(P)H pathway, together with GPX4 and GSH, inhibits phospholipid peroxidation and ferroptosis, offering broad prospects for the treatment of degenerative diseases caused by ferroptosis." (PMID 36090039, 2022). "On the other hand, GPX4 could be neuroprotective, and increasing GPX4 function could be a therapeutic strategy for neurodegenerative diseases." (PMID 32664576, 2020). "Therefore, GPX4 is a potential therapeutic target for degenerative diseases (activation of GPX4) and tumors (inactivation of GPX4)." (PMID 33294126, 2020). "Furthermore, the GPX4 protein concentration can be directly or indirectly regulated by Nrf2, and many studies have indicated that Nrf2 is crucial for both the onset and management of neurodegenerative diseases." (PMID 40589410, 2025).
neurodegenerative disease (continued). "Therefore, the induction of GPX4 expression and activity may be a strategy to protect against neurodegenerative diseases in this context." (PMID 37762411, 2023). "Ferroptosis has been widely studied in neurodegenerative diseases, traumatic brain injury, and EAE, where GPX4 downregulation has been observed." (PMID 40485847, 2025). "The accumulation of iron and lipid peroxidation was prevalent in neurodegenerative diseases, accompanied by the inhibition of glutathione (GSH) and glutathione peroxidase 4 (GPX4)." (PMID 35787281, 2022).
cardiovascular diseases (23 papers, 2020 to 2026). "Previous reports have shown that GPX4 variants are associated with cardiovascular diseases, particularly rs713041." (PMID 35453406, 2022). "Thus, GPX4 is essential to prevent the accumulation of toxic lipid hydroperoxides, which can trigger a mode of cell death termed ferroptosis, associated with many cardiovascular diseases." (PMID 39335584, 2024). "The decreased GPx4 enzyme activity seen with rs713041 carriers could explain, at least in part, the numerous reports showing the association of this variant with several cardiovascular diseases." (PMID 35453406, 2022). "Moreover, given the high complexity of transcriptional and post-transcriptional regulation of this selenoenzyme, it is important to ascertain if GPX4 variants which have previously been associated with cardiovascular disease (e.g., rs713041) influence GPx4 enzyme content or activity." (PMID 35453406, 2022). "Previous studies have confirmed the protective function of the NRF2/GPX4 axis in various cardiovascular diseases." (PMID 41030280, 2025). "Defects in GPX4 can cause Sedaghatian-type spinal metaphyseal dysplasia (SSMD), a severe genetic disease characterized by metaphyseal chondrodysplasia, cardiovascular disease, and neurologic defects." (PMID 38883711, 2024). "Although levels of inhibitors of ferroptosis, such as GPX4, are known to be reduced and expression of some other genes is known to be up-regulated during cardiovascular disease, the current testing methods are unsuitable for routine clinical diagnosis." (PMID 33537073, 2021). "Experimental studies have shown a role for a subset of redox-active selenoproteins, including GPx1, GPx3, GPx4, and Txnrd2, in protecting against complex cardiovascular diseases, in part, by attenuating the harmful effects of reactive oxygen species." (PMID 34579115, 2021). "In addition, previous research has shown that the expression of ferroptosis-related genes (RTN3, SLC25A1, and GPX4) in cardiovascular disease correlates with the serum HDL level." (PMID 38086802, 2023). "The role of GPX4 in cardiovascular disease is also gaining attention." (PMID 35906548, 2022). "Ferroptosis is a form of non-apoptotic cell death that is characterized by iron overload, glutathione (GSH) depletion, glutathione peroxidase 4 (GPX4) inactivation, and an imbalance in lipid and amino acid metabolism, which is essential in numerous diseases, including IS and cardiovascular disease." (PMID 37435058, 2023).
iron metabolism disorders (20 papers, 2019 to 2026). "Collectively, our results demonstrated that SIV infection causes intercellular iron disorder, inhibits system Xc−/GPX4 axis activation, and subsequently promotes cell lipid peroxidation and ferroptosis." (PMID 35715835, 2022). "Ferroptosis, a newly recognized regulatory form of cell death associated with lipid peroxidation and iron metabolism disorders, is attributed to lethal lipid reactive oxygen species (ROS) regulated by glutathione peroxidase 4 (GPX4), and is inhibited by iron chelators and lipophilic antioxidants." (PMID 36978979, 2023). "The ferroptosis is characterized by iron metabolism disorder, ROS accumulation, reduced glutathione levels and the inactivation of glutathione peroxidase 4 (GPX4)." (PMID 40709087, 2025). "Ferroptosis is primarily related to iron metabolism disorders, GPX4 antioxidation, and lipid peroxidation." (PMID 39834811, 2024). "Ferroptosis could be induced by iron metabolism disorder, lipid peroxidation accumulation, deficiency of glutathione (GSH) and inactivation of the antioxidant enzyme glutathione peroxidase 4 (GPX4)." (PMID 38407703, 2024). "Here, we summarize the main mechanisms involved in the process of ferroptosis such as accumulation of lipid ROS, inhibition of system Xc−, glutathione peroxidase 4 (GPX4) enzyme activity, and iron metabolism disorder." (PMID 34725564, 2021).
kidney diseases (16 papers, 2020 to 2025). "Ferroptosis is an iron-dependent programmed cell death associated with severe kidney diseases, linked to decreased glutathione peroxidase 4 (GPX4)." (PMID 38110369, 2023). "In conclusion, the current study showed that a lower GPX4 level was associated with more severe kidney disease and a higher risk of progression to ESKD in patients with DKD." (PMID 36275902, 2022). "Therefore, it is of interest to investigate the association of kidney GPX4 expression and renal disease severity as well as outcomes in DKD patients." (PMID 36275902, 2022). "Kidney tubule cell death is the predominant phenotype observed in global GPX4 knockout mice, highlighting the crucial involvement of GPX4 and ferroptosis in kidney disease." (PMID 39975561, 2025). "Overall, this study highlights a new autophagy-dependent ferroptosis module: hypoxia/ischemia-induced OTUD5 autophagy triggers GPX4 degradation, offering a potential therapeutic avenue for I/R-related kidney diseases." (PMID 38110369, 2023). "Subsequent studies will focus on “gpx4”, “autophagy”, “necroptosis” and “ferroptosis”, hoping to develop new targets in these pathways that have been explored and broaden the perspective of the treatment of kidney diseases." (PMID 39872050, 2024).
neurological diseases (10 papers, 2021 to 2026). "This iron deposition often results from altered cellular iron distribution, triggering Fenton chemistry and lipid peroxidation—processes tightly associated with the progression of neurological disease and accompanied by reductions in GSH and glutathione peroxidase 4 (GPX4) levels." (PMID 41425599, 2025). "Emerging evidence suggests that iron accumulation and lipid peroxidation, accompanied by reductions in GSH and glutathione peroxidase 4 (GPX4), the main regulator of ferroptosis, which levels can be found in various neurological diseases." (PMID 34987706, 2021).
bacterial infection (8 papers, 2015 to 2025). "However, the conditional depletion of GPX4 in myeloid cells increases death caused by bacterial infection in mice, suggesting a different role of GPX4 in bacterial innate immunity." (PMID 34078874, 2021). "In the case of bacterial infection, GPX4 expression in cells, particularly in macrophages, inhibits the activation of inflammasome." (PMID 40699725, 2025). "The findings shed light on the complex regulatory mechanisms of fish gpx4 in ferroptosis and inflammatory responses triggered by bacterial infection, and provide a scientific foundation for addressing the problem of A. hydrophila resistance in aquaculture." (PMID 40699725, 2025). "This suggested that the gpx4 gene may alleviate the damage inflicted on the organism during bacterial infection by modulating ferroptosis, thereby indicating a potential role for ferroptosis in specific microbial infectious diseases." (PMID 40699725, 2025). "The findings suggest that overexpression of the gpx4 gene may modulate the response to bacterial infection by inducing the inflammatory cytokines and suppressing ferroptosis." (PMID 40699725, 2025). "Results showed that GPX4 protein expression gradually decreased in the RAW264.7 cells at 12 h after bacterial infection, but then increased to normal levels at 24 h, which may reduce lipid peroxidation at the late stage of bacterial infection and protect macrophages from ferroptotic death." (PMID 35265210, 2022).
colorectal (7 papers, 2018 to 2026). "Mechanistically, CYP1B1 activates the AKT/SP-1 signaling pathway to upregulate GPX4 expression, thereby modulating colorectal carcinogenesis and progression." (PMID 41493849, 2026). "Notably, after genetically inhibiting Alox12 in mice, ferroptosis was dramatically inhibited compared with that in WT mice subjected to lung IR, as evidenced by decreases in ferric iron deposits, the levels of Fe2+ and MDA, and the increases in the GSH/GSSG ratio and the protein level of GPX4." (PMID 39268501, 2024).
genetic disease (6 papers, 2021 to 2025). "Today, PDHGPX is known as GPX4 and is recognized as a key mediator of a variety of human diseases including rare genetic disorders." (PMID 35453641, 2022). "In addition to genetic disorders, GPX4 has emerged as a hotspot in biomedical research following its recognition as a chief regulator of an emerging form of regulated cell death called ferroptosis." (PMID 35453641, 2022).
skeletal diseases (5 papers, 2022 to 2026). "Multiple core regulators involved in ferroptosis, such as GSH, GPX4, System Xc−, Nrf2, and ROS, have also been demonstrated to be involved in the development of skeletal diseases." (PMID 39712490, 2024). "In this review, we summarize the mechanism of ferroptosis, such as suppressing GPX4 expression and activating the lipid metabolism pathway; briefly list several inducers and inhibitors; and expound on the manifestations of iron death in skeletal diseases." (PMID 35941905, 2022).
mitochondrial disease (4 papers, 2019 to 2025). "To complement the model of acute RSL3-mediated pharmacological inhibition of GPX4 and provide further evidence of ferroptosis-related cellular pathology, we employed a second method of inducing ferroptosis that models the GSH depletion and oxidative stress observed in mitochondrial disease patients." (PMID 30921410, 2019).
adenocarcinoma (2 papers, 2019 to 2025). A common cancer characterized by the presence of malignant glandular cells. "The clonogenic ability, glutathione peroxidase 4 (GPX4) expression, and glutathione concentration were evaluated using HeLa and NCI-H1975 adenocarcinoma cell lines treated with erastin and/or X-ray irradiation." (PMID 31800616, 2019).
cardiac diseases (2 papers, 2025). "Specifically, STING autophagy induced by anoxia or ischemia-reperfusion leads to GPX4 degradation, thereby presenting a promising therapeutic target for heart diseases associated with I/R." (PMID 40274801, 2025).
gastrointestinal disease (2 papers, 2010 to 2025). A disease that occurs in the gastrointestinal system, excluding the hepatobiliary system. "Targeting GPX4 has emerged as a focused and versatile approach in managing ferroptosis-related gastrointestinal diseases." (PMID 40565780, 2025).
GI tumor (2 papers, 2025). "GI tumor cells commonly resist ferroptosis inducers (e.g., erastin, RSL3) and certain chemotherapeutics by upregulating glutathione peroxidase 4 (GPX4), thereby enhancing antioxidant capacity." (PMID 41229498, 2025).
infectious disease (2 papers, 2023 to 2026). A disorder directly resulting from the presence and activity of a microbial, viral, or parasitic agent in humans. "Factors such as GPX4 sites, glutathione and the Xc system have become new therapeutic entry points for infectious diseases." (PMID 38131014, 2023).
respiratory diseases (2 papers, 2024). "However, expression levels of SLC7A11 and GPX4 differ in a variety of respiratory diseases." (PMID 38562175, 2024).
brain diseases (1 paper, 2023). "GPX4 expression has been found to be down-regulated in many brain diseases." (PMID 38203455, 2023).
gynecological tumors (1 paper, 2025). "Recent studies indicate that RPLP2 deletion significantly correlates with ROS accumulation in gynecological tumors and induces ferroptosis mediated by GPX4 in HCC." (PMID 40564039, 2025).
hematological malignancies (1 paper, 2023). "However, it’s noteworthy that there are limited studies targeting GPX4 and AIFM2 in hematological malignancies to date." (PMID 38032290, 2023).
proliferative retinopathy (1 paper, 2022). "In addition, allele variants of the GSH system gene increase the risk of proliferative retinopathy in type 1 diabetics, further demonstrating the essential antioxidant role of GPX4 in retinal cells." (PMID 36284090, 2022).
vascular disorder (1 paper, 2024). A general term used to describe any disease affecting blood vessels]. "Inhibition of this ATGL activity via high-throughput sequencing the role GPX4 expression to prevent iron-dependent ferroptosis and IL-17A stimulating angiogenesis via promoting FAO angiogenic vascular disorders are new approaches that requires much attention." (PMID 38841622, 2024).
GPX4 also shares sentences with these, for which no sentence is quoted: renal failure (10 papers); dyslipidemia (6); lung squamous cell carcinoma (5); acute lymphoblastic leukemia (4); Ataxia (4); acute myocardial infarction (3); alcoholic liver diseases (3); Autoimmunity (3); coronary atherosclerosis (3); Encephalopathy (3); Parkinsonism (3); prostate adenocarcinoma (3); rectum adenocarcinoma (3); skin cutaneous melanoma (3); thyroid (3); abdominal aortic aneurysm (2); allergic disease (2); Bovine mastitis (2); brain hemorrhage (2); Burkitt lymphoma (2); Glucose intolerance (2); Huntington disease (2); hypothyroidism (2); idiopathic pulmonary fibrosis (2); infarction (2); Iron deficiency anemia (2); pulmonary tuberculosis (2); retinitis pigmentosa (2); Ureteral obstruction (2); uterine carcinosarcoma (2).
A further 110 diseases each share a sentence with GPX4 in 1 paper.